LINC01255 (long independently transcribed non-coding RNA 1255)
Gene: Long non-coding RNA gene on chromosome 18 (11,486,205 to 11,540,148, forward strand). Ensembl gene ENSG00000267252.
Diseases named in the same sentence as LINC01255 in open-access papers:
LINC01255 is named in the same sentence as 1 disease in open-access papers, as found by Europe PMC text mining. Sharing a sentence is not in itself a finding about the gene and the disease.
LINC01255 shares sentences with these, for which no sentence is quoted: testicular germ cell tumor (1 paper).